SATB2 (SATB homeobox 2)
Diseases named in the same sentence as SATB2 in open-access papers (continued):
Sharing a sentence is not in itself a finding about the gene and the disease.
tumor (continued). "Additional immunohistochemistry was performed, the tumor cells were positive for PAX8 and partly for CK7 and negative for SATB2 and CK20, confirming their gynecological and not colorectal origin." (PMID 33670088, 2021). "SATB2-low/absent CRCs were significantly enriched in higher pT/pN/pM and combined UICC-stages, right-sided tumours, carcinomas with lymphatic and blood vessel invasion as well as in tumours with positive margins (p < 0.001, respectively)." (PMID 34944797, 2021). "Immunostaining revealed that the tumor cells were positive for TLE1 and BCOR, and negative for cytokeratin (AE1/AE3), Desmin, CD45, S100, CD31, HMB45, and SATB2." (PMID 31702654, 2019). "Further, immunostaining of tumor cells was positive for TLE1 and BCOR, and negative for cytokeratin (AE1/AE3), Desmin, CD45, S100, CD31, HMB45, and SATB2." (PMID 31702654, 2019). "SATB2-overexpressing HPNE cells (HPNE/SATB2) formed tumors in Balb C nude mice, whereas HPNE/Empty vector cells did not form any tumor." (PMID 27472393, 2016). "SATB2 overexpressing HPNE cells (HPNE/SATB2) formed tumors (evident by tumor volume and tumor weight) in Nude mice, whereas HPNE/Empty vector cells did not form any tumor in mice." (PMID 27472393, 2016). "SATB2-transformed HPNE cells gained the phenotypes of CSCs and also formed tumors in nude mice, whereas HPNE/empty vector group did not form any tumor in mice." (PMID 27472393, 2016). "When the other main histological confounders (WHO grade, tumour budding, CRC subtypes) were excluded from the Cox-regression analysis, SATB2-expression remained a prognostic factor independent of UICC stage, age, gender, resection status and MSI-status (DSS: 0.029, HR:1.32)." (PMID 34944797, 2021). "In multivariate analyses (including age, gender, resection status, UICC stage, MSI-status, WHO grade, tumour budding, CRC subtypes and SATB2-groups) SATB2-expression was not an independent prognostic factor (e.g., DSS: p = 0.1, hazard ratio: 1.25) in the overall cohort comprising all CRCs." (PMID 34944797, 2021). "Another explanation could be that SATB1 and SATB2 exert synergistic effects in the majority of CRC, as reflected in their positive interrelationship, but that, in the absence of SATB2, SATB1 may reprogramme the tumours towards a more malignant phenotype." (PMID 22935204, 2012). "If CDX2 and SATB2 are both negative, or if CK7 is positive but CK20 and TRPS1 are negative, third-tier immunostains including p63, GATA3, uroplakin II/III, PSA, and NKX3.1 should be performed to further classify the tumor as urothelial or prostatic secondary EMPD." (PMID 41463263, 2025). "Furthermore, the tumor cells were positive for cytokeratin (CK) 19; partially positive for thyroid transcription factor-1 (TTF-1); and negative for Pax-8, Napsin A, CDX-2, SATB2, and terminal deoxynucleotidyl transferase (TdT)." (PMID 33847622, 2021).
cancer (58 papers, 2012 to 2026). A tumor composed of atypical neoplastic, often pleomorphic cells that invade other tissues. "Other cancer-related gene mutations identified by our WES analysis included SATB2, NOTCH3, STAG2 and TET2." (PMID 38201285, 2023). "Among SATB2-positive SBAs, SATB2 expression in cancer-associated dysplasia was observed in only one case." (PMID 33228145, 2020). "In breast cancer, SATB2 mRNA expression is significantly associated with cancer progression and poor survival." (PMID 27472393, 2016). "SATB2 gene is overexpressed in colorectal, breast, lung, liver, neuroendocrine, and pancreatic cancer, and has been associated with cancer progression and poor survival." (PMID 38891096, 2024). "CDX2 expression is reportedly retained in SSLs but later decreases in serrated pathway‐associated carcinomas;11, 32 thus mechanisms downregulating SATB2 and CDX2 may also differ." (PMID 37036163, 2023). "SATB2 has been increasingly linked to colorectal and head and neck cancers." (PMID 26701851, 2016). "Previous studies have identified SATB2 as a target of miR-31 in cancer-associated fibroblasts." (PMID 24386467, 2013). "SATB2, a nuclear matrix-associated transcription factor and a member of the family of special AT-rich binding proteins, has recently been shown to be expressed in normal cells of the lower gastrointestinal tract and in cancer cells of colorectal origin." (PMID 22412953, 2012). "SATB2 (special AT-rich binding protein - 2), as a type of TcoF, could induce epithelial–mesenchymal transition and metastasis and be used as a diagnostic biomarker for cancer." (PMID 35734428, 2022). "Only two cases expressed SATB2 in the glandular component, indicating 0.53% positivity in this cancer group." (PMID 41321186, 2025). "Since prostate CSCs play a crucial role in cancer initiation, progression, and metastasis, we also examined the effects of SATB2 knockdown on stemness." (PMID 38891096, 2024). "CDH17 and SATB2 were excellent potential biomarkers for diagnosing metastatic colorectal adenocarcinoma and pulmonary enteric malignancy." (PMID 37719843, 2023). "In this study, they observed that miR-34a-EVs led to a significant inhibition of cancer cell proliferation, migration and invasion by downregulation of SATB2 expression (the special AT-rich sequence-binding protein 2)." (PMID 37242569, 2023). "We also observed the significant inhibition of miR-31-targeted genes following GBK treatment, including RHOA, WAVE3, and SATB2, with functions closely related to cancer cell invasion, migration, and proliferation." (PMID 36313626, 2022). "This contradiction illustrates the complex role of SATB2 in cancer biology, where it has been primarily described as a transcription factor in craniofacial embryogenesis." (PMID 36351995, 2022). "We have recently demonstrated that the SATB2 gene can induce the transformation of normal epithelial cells into cancer stem cells." (PMID 35152538, 2022). "Exosomal miR-31-5p plays a critical role in cancer progression by decreasing SATB2 expression and increasing the activity of MEK/ERK pathway." (PMID 34074322, 2021). "Within the SATB family, both SATB-1 and SATB-2 were investigated in cancer progression and are involved in human placenta development by promoting trophoblast stem cell renewal and inhibiting their differentiation." (PMID 34829454, 2021). "Carcinoma tissue was 100% positive for SATB2, 95% positive for CK20 and positive for KI67 with 50% being highly positive and 25% expressing moderate levels of KI67." (PMID 32927768, 2020). "Increasing researches have indicated that SATB2 was aberrantly expressed in a variety of malignant tumors." (PMID 30627547, 2018). "In contrary, downregulation of SATB2 expression was shown to be associated with enhanced cell growth, metastasis and poor prognosis in CRC56, 57 and overexpression of SATB2 repressed cancer cell proliferation, migration and invasion by inhibiting ERK558." (PMID 28887549, 2017).
cancer (continued). "SATB2 is also a sensitive and highly specific marker for CRC, functioning as a diagnostic marker that clinically distinguishes CRC from other types of cancer." (PMID 29254139, 2017). "HCT-116 and HT-29 cancer cells and CSCs were transduced with either scrambled or SATB2 shRNA lentiviral particles, and SATB2 expression and cell growth were measured." (PMID 28887549, 2017). "Recent studies have identified certain microRNAs (miRNAs) which regulated cancer cell progression, and metastasis by modulating the expression of SATB2." (PMID 28887549, 2017). "While SATB2 is typically only expressed in embryonic tissues, previous studies have found SATB2 to be upregulated in some human cancers and in BEAS-2B clones transformed by nickel, chromium (VI), arsenic, and vanadium." (PMID 27186882, 2016). "SATB1 expression in most cancers including CRC is associated with progression, poor prognosis and microsatellite instability (MSI), and SATB1 expression correlates with the loss of SATB2 expression." (PMID 26701851, 2016). "Aberrant expression of MARBPs such as PARP, CUTL1, HMG (I/Y), RUNX1-3, SATB1, SATB2, PcG (polycomb group of proteins), SAFB1/2, SMAR1 etc. has been implicated in several cancers." (PMID 26325577, 2015). "Kaplan–Meier analysis and Cox proportional hazards modelling were used to explore the impact of SATB2 expression on cancer-specific survival (CSS) and overall survival (OS)." (PMID 22333599, 2012). "This study showed the first evidences that the status of SATB2 expression in carcinoma tissues is much lower than that in paracarcinoma tissues in LSCC, and SATB2 is an independent prognostic factor for LSCC patients." (PMID 22815795, 2012). "SATB2-Ir was observed in the nuclei of epithelial cells, as well as cancer cells." (PMID 40076993, 2025). "The effects of SATB2 action on these cancers’ cell lines promoted their growth and progression." (PMID 40076993, 2025). "Furthermore, numerous studies have indicated that the dysregulation of SATB2 is in connection with the malignant progression of cancer cells." (PMID 40078194, 2025). "So, it seems that SATB2 expression is not only tissue- and cancer-type dependent but may also be racial/ethnic-specific." (PMID 40076993, 2025). "Based on these data, SATB2 can be used as a biomarker and therapeutic target for cancer." (PMID 38891096, 2024). "Similarly, in other models of cancer, we have demonstrated that overexpression of SATB2 induced EMT, and SATB2 knockdown in CSCs inhibited EMT characteristics." (PMID 38891096, 2024). "A comprehensive illustration on spectrum of primary cancer types in CK7(+)/CDX-2(+)/SATB2(+) tumors might assist in primary tumor identification as well." (PMID 36463302, 2022). "Suppression of SATB2 expression in ethanol‐transformed hepatocytes by Crisp/Cas9 technique inhibited markers of stem cells and pluripotency, suggesting an essential role of SATB2 in generating the properties of cancer stem‐like cells." (PMID 35152538, 2022). "Although the expression of SATB2 was absent or very low in human pancreatic normal ductal epithelial cells, mammary epithelial cells, and colorectal epithelial cells, overexpression of SATB2 in these normal cells induced malignant transformation, suggesting an oncogenic role of SATB2 in cancer." (PMID 34859959, 2022). "SATB2 may be a driving force for developing cancer stem‐like phenotypes in damaged hepatocytes where induction of stem cell markers (CD44, CD90, EpCAM, AFP and LGR5) and pluripotency maintaining factors (POU5F1/Oct4, Sox‐2, Nanog and KLF4) was prominent." (PMID 35152538, 2022). "We observed that miR-31-5p could be the better biomarker to predict cancer metastasis in clinics with AUC of 0.844, AUC of SATB2 + miR-31-5p group and SATB2 group is 0.835 and 0.767, respectively." (PMID 34074322, 2021).
cancer (continued). "Although the association between SATB2 and outcome seems weak, CK7/CK20 expression efficiently stratifies SBA patient prognosis and may also be helpful to identify MMR-d cancers generally associated with a favorable outcome." (PMID 33228145, 2020). "SATB2 has been shown to regulate the oncogenesis in various cancers." (PMID 31602781, 2019). "Evidence suggests that SATB2 plays diverse and important roles in various cancers." (PMID 31492160, 2019). "To investigate the clinical relevance of the expression of miR-449a, miR-34a and their target gene SATB2, we detected their expression levels by qPCR in 50 paired human colorectal normal and cancer tissues which included 10 stage I, 15 stage II, 10 stage III and 15 stage IV samples, respectively." (PMID 29254139, 2017). "Our studies suggest that SATB2 can promote cancer cell EMT and also metastasis." (PMID 28887549, 2017). "Different staining patterns for SATB1 and SATB2 were obtained on normal and cancer tissues." (PMID 25326863, 2014). "The status of SATB2 protein in carcinoma tissues is much lower than that in paracarcinoma tissues." (PMID 22815795, 2012). "Nevertheless, it has also been noted that SATB2 functions may be related to the type of cancer." (PMID 40076993, 2025). "SATB2, as a transcriptional co-gene, may affect the radioresistance of cancer cells." (PMID 40078194, 2025). "Furthermore, the role of SATB2 as a biomarker for certain cancers has been suggested." (PMID 38891096, 2024). "In addition, subsequent studies suggest that Villin and SATB2 can also be used as important complementary tools for the differential diagnosis of carcinoma of unknown primary origin." (PMID 35444939, 2022). "Moreover, the role of SATB2 in transcriptional regulation and as a driver of epigenetic events may well differ between different cancer forms." (PMID 22333599, 2012). "The upregulation of SATB2 in HPNE cells was sufficient to induce malignant transformation in vitro, and those transformed cells gained the phenotypes of CSCs by expressing cancer stem cell markers and pluripotency‐maintaining factors." (PMID 34859959, 2022). "Immunohistochemical analysis of 1882 CRC tissues from nine independent cohorts showed that 85% of tumors were positive for SATB2 and 97% for SATB2 and/or cytokeratin 20, suggesting that SATB2 is a highly sensitive marker to distinguish CRC from other cancers." (PMID 31492160, 2019). "SATB2, a transcription factor involved in chromatin remodeling, is known to be downregulated in CRC, and can distinguish CRC from other cancer types with high sensitivity." (PMID 31586988, 2019). "The effects of SATB2 expression on metastasis and prognosis of CRC are different from those on other types of cancer." (PMID 26701851, 2016). "The T-lineage enriched global chromatin organizer SATB1 is a close homologue to SATB2, and expression of SATB1 has been reported to correlate with poor prognosis in several cancer forms, e.g. breast, gastric and liver cancer." (PMID 22935204, 2012). "Although SATB1 and SATB2 are homologous genes in which their amino acid sequence exhibits 60% homology, and SATB1 is a potential oncogene, the role of SATB2 in cancer is still unclear." (PMID 22815795, 2012). "Immunohistochemical SATB2 expression was assessed in 527 incident CRC cases from the Malmö Diet and Cancer Study." (PMID 22333599, 2012). "Nuclear SATB2 immunostaining was observed in epithelial cells in 98/104 (94.2%) of non-involved colorectal tissues, while in cancer cells, SATB2-Ir was detected in 84/104 (80.8%) CRC cases." (PMID 40076993, 2025). "Our data showed that SATB2 is highly expressed in human prostate CSCs and cancer cell lines, but not in human normal prostate epithelial cells." (PMID 38891096, 2024). "Based on these studies it is not clear why certain miRNAs would promote or inhibit cancer progression and metastasis by suppressing SATB2." (PMID 28887549, 2017).
cancer (continued). "Since SATB2 is not expressed in normal CRL-1831 cells, but it is highly expressed in human CRC cell lines, and primary cancer tissues, it can be used as a diagnostic and prognostic biomarker of CRC." (PMID 28887549, 2017). "We have identified, for the first time, that SATB2 is highly expressed in human pancreatic CSCs (Pan CSCs) and cancer cell lines, but not in human pancreatic normal ductal epithelial cells." (PMID 27472393, 2016). "Furthermore, survival analyses of patients across various cancer types revealed that the expression of SATB family proteins, particularly SATB1 and SATB2, correlates with tissue-specific patterns and may significantly influence disease prognosis." (PMID 40689929, 2025). "However, the direct MAR‐binding targets of SATB2 in cancers particularly in GBM have not been determined." (PMID 33124191, 2020). "The main goal of the paper is to examine the molecular mechanisms by which SATB2 regulates transformation of human pancreatic normal ductal epithelial (HPNE) cells, and assess whether transformed HPNE cells gained the phenotypes of cancer stem cells (CSCs)." (PMID 27472393, 2016). "Along this line, while some studies have suggested antagonistic effects of SATB1 and SATB2, it cannot be ruled out that SATB1 and SATB2 both increase chemotherapy sensitivity in the here examined types of cancer." (PMID 25323550, 2014). "Second, data on cancer adjuvant treatments were not available, and we could not assess whether CDX2 or SATB2 expression would predict response to specific treatments." (PMID 39998677, 2025).
adenocarcinoma (22 papers, 2014 to 2025). A common cancer characterized by the presence of malignant glandular cells. "We next compared the expression of SATB2 in human prostate normal and adenocarcinoma tissues by IHC." (PMID 38891096, 2024). "Possibly through interaction with the Wnt pathway, SATB2 is also involved in tumorigenesis of many adenocarcinomas." (PMID 38201285, 2023). "SATB2 is widely used by pathologists as a sensitive and specific marker of a colorectal origin in adenocarcinomas." (PMID 36351995, 2022). "The expression of SATB2 is more specific to adenocarcinoma of the lower gastrointestinal tract origin compared to the expression of CDX2." (PMID 32867793, 2020). "In one study, SATB2 expression was diffuse and strongly positive in 96.8% of adenocarcinomas of colorectal origin and positive in only 6.7%, 0%, and 4.2% of adenocarcinomas of esophagus, stomach, and pancreas, respectively." (PMID 27738541, 2016). "Moreover, while there were no significant treatment predictive effects of SATB2 expression in I-type adenocarcinoma, it is noteworthy that SATB2-positive I-type cases receiving adjuvant chemotherapy had no recurrences or fatalities during the follow up period." (PMID 25323550, 2014). "SATB2 is constitutively expressed in the physiological colorectal mucosa and a majority of colorectal adenocarcinomas and is widely used as a routine immunohistochemical marker indicating a colorectal origin to differentiate colorectal adenocarcinomas from other adenocarcinoma primaries." (PMID 36351995, 2022). "For adenocarcinomas, an intestinal-type immunophenotype (CK20/CDX2/SATB2) should prompt GI work-up to exclude metastasis." (PMID 41375020, 2025). "For adenocarcinoma, particularly intestinal type, an immunopanel including CK7, CK20, CDX2, and SATB2 (± PAX8) should be interpreted alongside a directed GI work-up to exclude metastasis." (PMID 41375020, 2025). "All LAMN cases exhibited a similar immunoprofile (CK20+, CDX2+, PAX8−), while the adenocarcinoma case co-expressed CDX2 and SATB2 with negativity for CK7, CK20 and PAX8." (PMID 31771640, 2019). "As it was shown previously, ITAC and adenocarcinomas of the intestinal tract show to a great extent morphological similarities, as well as overlapping immunohistochemical expression profile, including typically positive staining for CK20, CDX2, villin, MUC2 and SATB2." (PMID 35015192, 2022). "Finally, the differential diagnosis of ITAC from sinonasal nonintestinal adenocarcinomas is supported by immunohistochemistry for CK20, CDX-2, villin and SATB-2 which only stain ITACs." (PMID 28321774, 2017).